ITM2A (integral membrane protein 2A)
Diseases named in the same sentence as ITM2A in open-access papers (continued):
Sharing a sentence is not in itself a finding about the gene and the disease.
tumor (18 papers, 2017 to 2025). "The downregulation of HLA-DQA1, HLA-DOB, and ITM2A, which are associated with immune evasion and tumor progression, is consistent with the immune-excluded phenotype observed in the mesenchymal-like (C5) and aggressive basal/squamous-like (C4) subtypes." (PMID 40867248, 2025). "Through a comprehensive pan-cancer analysis, our study identified aberrant expression of ITM2A across various tumor types, with a significant association with the TIME." (PMID 39720726, 2024). "Similarly, ITM2A has been shown to be a tumor suppressor and is associated with PD-L1 in breast cancer." (PMID 39720726, 2024). "This suggests that low ITM2A expression may be associated with a less active immune response, which may result in a decreased immune cell infiltration at the tumor site, such as reduced numbers and activities of T cells, B cells, and macrophages." (PMID 39720726, 2024). "The M17 gene module comprises core genes including TIMP1, TFF2, ITM2A, SPINK1, and TSPAN8, intimately associated with tumor stemness maintenance and invasion-metastasis capacity." (PMID 41450464, 2025). "The tumor-suppressive effect of CXCR1 is unclear but seems to correlate with an increase expression of the tumor suppressor ITM2A." (PMID 39766038, 2024). "By analyzing the clinical data, we found that ITM2A expression was higher in the early stages of the tumor, and its expression level began to decrease as the tumor stage progressed." (PMID 39720726, 2024). "Compared with the vector group, the tumor volumes of the ITM2A overexpression were significantly decreased." (PMID 39720726, 2024). "To determine the effect of ITM2A in MDA-PCa-2b-CXCR1 tumor growth, we first attempted to generate MDA-PCa-2b cell lines deficient in ITM2A expression." (PMID 39766038, 2024). "Immunohistochemistry experiments further supported this finding by demonstrating that the protein expression of ITM2A was also reduced in tumor tissues." (PMID 39720726, 2024). "To gain a deeper understanding of the difference in ITM2A expression in normal and tumor tissues, we analyzed the TCGA combined with GTEx pan-cancer data using XENA download." (PMID 39720726, 2024). "It was proved that ITM2A overexpressed tumors were notably smaller than ITM2A normally expressed tumor with respect to MRI test and tumor size." (PMID 33680917, 2020). "On the other hand, ITM2A is probably closely related to TILs and shapes the tumor microenvironment, which influences patients’ outcomes and treatment strategy once it is proved to play roles in T cells development." (PMID 33680917, 2020). "Before this study, there were a handful of studies that investigated the functions of ITM2A in tumor." (PMID 33680917, 2020). "From RNA-Seq analysis, we found that tumour suppressors such as Ccdc80, Itm2a, and Sfrp1 were significantly up-regulated by the combination treatment of vactosertib with nal-IRI/5-FU/LV compared to the control group and the nal-IRI/5-FU/LV group." (PMID 32076068, 2020). "In B-ALL patients, 173 candidates were identified to be significantly associated with GATA3 expression, including some reported GATA3-related genes (e.g., ITM2A) and well-known tumor-related genes (e.g., STAT4)." (PMID 28415601, 2017). "Gene Ontology functional annotation and KEGG pathway enrichment analysis indicated that ITM2A may coordinate anti-tumor immune responses by regulating copper ion metabolic reprogramming and immune checkpoint networks." (PMID 40657365, 2025). "In the context of cancer, alterations in ITM2A may contribute to tumor progression by affecting cellular responses to stress and altering the balance between cell survival and programmed cell death." (PMID 40867248, 2025). "Interestingly, the overexpression of ITM2A in MDA-PCa-2b cells (MDA-PCa-2b-ITM2A-GFP) inhibited tumor growth similar to that of MDA-PCa-2b-CXCR1." (PMID 39766038, 2024). "However, the overexpression of ITM2A in MDA-PCa-2b cells decreased tumor growth similar to that of MDA-PCa-2b-CXCR1 cells." (PMID 39766038, 2024).
tumor (continued). "Additionally, the overexpression of ITM2A has been found to inhibit tumor cell proliferation and reduce their capacity for invasion and migration." (PMID 37895185, 2023). "ITM2A was downregulated in tumor compared with normal specimens." (PMID 34872446, 2021). "Moreover, combination treatment of vactosertib with nal-IRI/5-FU/LV induced well-known tumour suppressors ITM2A and SFRP1." (PMID 32076068, 2020). "Since the composition of TIME has an important impact on tumor development and subsequent treatment, we performed TIME scoring on TCGA-HNSC samples and analyzed its correlation with ITM2A expression." (PMID 39720726, 2024). "In summary, the expression of ITM2A was markedly diminished in the tissues of patients with HNSC, and this reduction was significantly correlated with adverse prognosis and tumor progression." (PMID 39720726, 2024). "Comparison of genes differentially expressed between the subcluster C9 of exhausted CD8+ cells from tumors and normal tissues showed GNLY and ITM2A were highly expressed in normal tissues, and high expression of FABP5 and RPS6 was exhibited in tumor tissues." (PMID 35874785, 2022). "Kaplan-Meier analysis indicated that patients presenting with reduced ITM2A expression exhibited poor overall survival, and expression significantly correlated with age, progesterone receptor status, TNM classification and tumor stage." (PMID 31438969, 2019). "CXCR1 expression, not CXCR2, was shown to upregulate the tumor suppressor ITM2A to diminish cell proliferation and inhibit tumor growth." (PMID 39766038, 2024). "Moreover, we found that ITM2A expression significantly correlates with age, TNM classification and tumor stage." (PMID 31438969, 2019). "We found that the mean methylation level of ITM2A, GALNTL1, FAM107A, and MFAP4 was significantly higher in tumor tissue while the methylation level of PGM5 was higher in normal tissue." (PMID 33376725, 2020). "We found that decreased expression of ITM2A significantly correlates with age, progesterone receptor (PR) status, TNM classification and tumor stage but not with estrogen receptor (ER) status and human epidermal growth factor receptor 2 (HER2) levels." (PMID 31438969, 2019).
cancer (9 papers, 2020 to 2025). A tumor composed of atypical neoplastic, often pleomorphic cells that invade other tissues. "Based on the TIMER database, there were more than 10 types of cancer with lower expression of ITM2A." (PMID 33680917, 2020). "Finally, we analyzed the immune cell infiltration by ssGSEA algorithm using TCGA pan-cancer data, and correlation analysis between ITM2A and immune infiltration matrix data was performed using Spearman’s method." (PMID 39720726, 2024). "Among the specifically expressed genes of each subgroup, PDLIM1 correlated only with three other cancer stem cell markers, namely PDGFRA, RBP1, and ITM2A." (PMID 39548074, 2024). "Then, a pan-cancer differential expression analysis was performed, and we found that genes such as CXCL13, ITM2A, NR3C1, SRGN, COTL1, and PDCD1 were significantly up-regulated in SC-2 cells compared with other cells in at least five cancer types, but not in SC-10 cells." (PMID 36049666, 2023).
ITM2A also shares sentences with these, for which no sentence is quoted: acute lymphoblastic leukemia (1 paper); adenocarcinoma (1); adenosquamous carcinoma (1); cleft palate (1); diffuse large B-cell lymphoma (1); follicular lymphoma (1); glioblastoma (1); Graves disease (1); lung carcinoma (1); lymph node metastasis (1); psychiatric disorder (1); squamous carcinoma (1); thymoma (1); thyroid-associated ophthalmopathy (1); X-linked deafness (1); X-linked intellectual disability (1).